PTPN5 (protein tyrosine phosphatase non-receptor type 5)
Description:
May regulate the activity of several effector molecules involved in synaptic plasticity and neuronal cell survival, including MAPKs, Src family kinases and NMDA receptors.
Synonyms: STEP; PTPSTEP; STEP61
Tractability: Small molecule: a structure with a bound ligand is known; a high-quality ligand is known. Antibody: UniProt predicts a signal peptide or a membrane-spanning region; its Gene Ontology location is reachable by antibodies, with medium confidence. PROTAC: its protein half-life has been measured; a small molecule that binds it is known.
Target class: Tyrosine protein phosphatase; Enzyme; Phosphatase; Protein Phosphatase
Chemical probes: BI-0314 (high quality)
Gene: Protein-coding gene on chromosome 11 (18,727,928 to 18,792,721, reverse strand). Ensembl gene ENSG00000110786.
Subcellular location: Endoplasmic reticulum membrane
Subcellular location (Human Protein Atlas): Endoplasmic reticulum
Pathways (Reactome):
Immune System: Interleukin-37 signaling
Gene Ontology:
Molecular function: phosphotyrosine residue binding; protein binding; protein kinase binding; protein tyrosine phosphatase activity
Biological process: protein dephosphorylation; signal transduction
Cellular component: cell junction; cytosol; membrane; nucleoplasm; plasma membrane; endoplasmic reticulum membrane
Genetic constraint (gnomAD): Loss-of-function variants: 27 observed, 64.21 expected, observed/expected ratio (o/e) 0.42, 90% interval 0.31 to 0.58. The upper end of that interval is the gene's LOEUF score, 0.58, which puts it in group 2 of 6, group 1 being the genes least tolerant of losing a copy. Missense variants: 611 observed, 689.11 expected, observed/expected ratio (o/e) 0.89, 90% interval 0.83 to 0.95. Synonymous variants: 248 observed, 277.54 expected, observed/expected ratio (o/e) 0.89, 90% interval 0.81 to 0.99.
Homologues: Orthologues: chimpanzee PTPN5 (99% identical), guinea pig PTPN5 (88% identical), rat Ptpn5 (88% identical), pig PTPN5 (87% identical), mouse Ptpn5 (86% identical), macaque PTPN5 (85% identical), rabbit PTPN5 (72% identical), tropical clawed frog ptpn5 (57% identical), zebrafish ptpn5 (54% identical). Paralogues in human: PTPRR (41% identical), PTPN7 (32% identical), PTPRB (25% identical), PTPRF (25% identical), PTPRS (24% identical), PTPRJ (24% identical), PTPN13 (24% identical), PTPRT (23% identical), PTPRD (23% identical), PTPRK (23% identical), PTPRM (23% identical), PTPRH (22% identical), and 23 more.
Diseases named in the same sentence as PTPN5 in open-access papers:
PTPN5 is named in the same sentence as 41 diseases in open-access papers, as found by Europe PMC text mining. Sharing a sentence is not in itself a finding about the gene and the disease. The quoted sentences say what the papers report.
schizophrenia (8 papers, 2015 to 2026). A major psychotic disorder characterized by abnormalities in the perception or expression of reality. "We highlight the striatal-enriched tyrosine phosphatase STEP (PTPN5) as a case study illustrating how selective phosphatase modulation can restore synaptic signaling in schizophrenia-relevant models." (PMID 41898681, 2026). "In Fragile X syndrome and schizophrenia, protein levels of STEP encoding by Ptpn5 are significantly increased." (PMID 35058780, 2021).
Alzheimer disease (7 papers, 2014 to 2023). A progressive, neurodegenerative disease characterized by loss of function and death of nerve cells in several areas of the brain leading to loss of cognitive function such as memory and language. "Abnormal alterations in PTPN5 activity are associated with several neurological disorders, and it is known that upregulation of PTPN5 may have a causal role in Alzheimer’s disease." (PMID 37953885, 2023). "Striatal-enriched tyrosine protein phosphatase (STEP), encoded by the Ptpn5 gene, is a neuron-specific phosphatase that regulates synaptic function and plasticity, whereas its dysregulation is associated with neurodegenerative diseases including Alzheimer’s disease (AD)." (PMID 32707818, 2020). "Inhibition of PTPN5 reverses cognitive deficit impairment in mouse models with Alzheimer’s disease." (PMID 35681895, 2022).
breast carcinoma (4 papers, 2018 to 2022). "High levels of PTPN5 expression were strongly associated with good overall survival for all breast cancer patients which were followed for 20 years (p<0.0008)." (PMID 29590203, 2018). "Further, PTPN5 expression is strongly associated with good clinical outcome in tamoxifen treated human breast cancer patients suggesting that PTPN5 may represent a novel biomarker of tamoxifen response in human breast cancer." (PMID 29590203, 2018). "PTPN5 mRNA expression was significantly reduced in all subtypes of breast cancer patients when compared to normal samples." (PMID 29590203, 2018). "To further explore the clinical significance of PTPN5 expression in human breast cancer patients, we queried the TCGA dataset to examine levels of PTPN5 expression in distinct molecular subtypes of BC." (PMID 29590203, 2018). "Functional validation of PTPN5 in tamoxifen sensitive, tamoxifen resistant and TNBC cells shows that activation of PTPN5 suppressed the EGF-induced MAPK signaling pathway in breast cancer cells." (PMID 29590203, 2018). "The activation of PTPN5 inhibits the MAPK signaling pathway induced by EGF in breast cancer cells." (PMID 35154122, 2022). "To determine whether PTPN5 controls EGF-induced MAPK signaling in human breast cancer cells, we assessed the phosphorylation status of MAPK in various breast cancer cells by forced expression of PTPN5." (PMID 29590203, 2018). "We show that Ptpn5 is a novel tamoxifen regulated target gene which is upregulated in MECs after transient tamoxifen exposure and displays tumor suppressor activity in human breast cancer cells." (PMID 29590203, 2018). "We found that PTPN5 expression is strongly correlated with improved DMFS in tamoxifen treated breast cancer patients suggesting that PTPN5 may represent a novel prognostic marker of tamoxifen response." (PMID 29590203, 2018). "In addition, we also assessed the prognostic value of PTPN5 mRNA expression in various breast cancer subtypes using the Kaplan Meier Plotter database." (PMID 29590203, 2018). "Next, we investigated whether restoration of PTPN5 inhibits growth of breast cancer cells." (PMID 29590203, 2018). "PTPN5 act as a tumor suppressor in breast cancer, but previous studies have not found differences in the expression of PTPN5 between AML and normal samples." (PMID 36699453, 2022). "Finally, using breast cancer classification, we identified good prognostic effect of over expression of PTPN5 in luminal B (P<0.0004) but not in other subtypes of breast cancer patients." (PMID 29590203, 2018). "PTPN5 is in the same non-receptor Cys-based classical PTPs as PTPN1 and PTPN11, which promoted tumorigenesis in ovarian cancer, gastric cancer, prostate cancer, breast cancer, leukaemia, colorectal cancer and uveal melanoma." (PMID 32928212, 2020).
colorectal cancer (3 papers, 2008 to 2020). A primary or metastatic malignant neoplasm that affects the colon or rectum. "Our results provide evidence for frameshift mutations in six of these PTP genes (PTPN21, PTPRS, PTPN5, PTPN23, PTPRA, PTPRE) affecting about 32% of MSI-H colorectal cancers." (PMID 19000305, 2008). "For colorectal cancer (CRC), PTPN2, PTPN21 and PTPN22 levels were correlated with incidence; expression of PTPN5, PTPN12, and PTPN14 was correlated with TNM stage and N stage; high PTPN5 or PTPN7 expression was associated with increased hazards of death." (PMID 32536826, 2020).
neuroblastoma (3 papers, 2021 to 2023). Neuroblastoma (NB) is the most common solid, extracranial childhood tumor. "Interestingly, a distinct pattern of PTPRR, PTPN5, and PTPN7 mRNA expression was observed in human neuroblastoma cell lines upon retinoic acid differentiation, with down-regulation of PTPN5 and up-regulation of PTPN7 and, to a lesser extent, PTPRR." (PMID 34957126, 2021).
brain injury (2 papers, 2021 to 2022). Acute and chronic (see also brain INJURIES, CHRONIC) injuries to the brain, including the cerebral hemispheres, CEREBELLUM, and brain STEM. "Additionally, high PTPN5 activity decreases with aging, whereas PTPN5 deficiency induces neuronal inflammation and exacerbates ischemic brain injury." (PMID 35681895, 2022).
Huntington disease (2 papers, 2021 to 2022). Huntington disease (HD) is a rare neurodegenerative disorder of the central nervous system characterized by unwanted choreatic movements, behavioral and psychiatric disturbances and dementia. "We also measured the expression of 24 phosphatases in the striatal proteome, one of which was significantly downregulated in Huntington’s disease compared with WT mice in SH: PTPN5." (PMID 36523271, 2022).
breast tumors (1 paper, 2022). "In vivo studies revealed that PTPN5 inhibits the growth of breast tumors by blocking the epidermal growth factor (EGF)-induced MAPK signaling pathway." (PMID 35681895, 2022).
colon adenocarcinoma (1 paper, 2020). "In our study, PTPN5 and PTPN7 were found to be correlated with prognosis of colon adenocarcinoma patients, while PTPN6 and PTPN13 were statistically associated with the prognosis of STAD." (PMID 32536826, 2020).
epilepsy (1 paper, 2024). A brain disorder characterized by episodes of abnormally increased neuronal discharge resulting in transient episodes of sensory or motor neurological dysfunction, or psychic dysfunction. "Nav2, Ptpn5, Ldha, and Dbx1 are deemed higher priority as they have a direct biological association with seizures or epilepsy, while Prmt3 and Slc6a5 have an indirect association." (PMID 38862622, 2024).
glaucoma (1 paper, 2022). Increased pressure in the eyeball due to obstruction of the outflow of aqueous humor. "Genes co-expressed with PTPN5 were correlated with “Retinal ganglion cell damage in glaucoma”, “Development_Transcriptional regulation of megakaryopoiesis”, and “Development_Growth hormone-releasing hormone (GH-RH) signaling”." (PMID 36556168, 2022).
mastitis (1 paper, 2022). Inflammation of breast tissue during lactation or postpartum due to an obstructed duct or infection. "Our RNA-seq results revealed that PTPN5 modulates inflammation by inhibiting the MAPK signaling pathway in the mammary gland of dairy cows with mastitis." (PMID 35681895, 2022). "Therefore, silencing miR-375 alleviates mastitis in cows by promoting PTPN5 expression and while inhibiting the MAPK signaling pathway." (PMID 35681895, 2022).
myopia (1 paper, 2021). "In the current study, PTPN5 rs1550870 was significantly associated with incident myopia and significant myopic shift." (PMID 34122509, 2021). "Based on the results from GMDR, the one-locus model PTPN5 rs1550870 was significantly associated with incident myopia, which was consistent with the results of the single-locus analysis." (PMID 34122509, 2021). "PTPN5 rs1550870 has been found to be strongly associated with myopia in a large-sample GWAS based on a European population." (PMID 34122509, 2021). "PTPN5 rs1550870 was found to be strongly associated with myopia only in a large-sample GWAS based on a European population (P = 9.9 × 10–13)." (PMID 34122509, 2021). "After adjusting for confounding factors with 10,000 permutations, children with the CT or TT genotype of PTPN5 rs1550870 were more susceptible to myopia than those with the CC genotype (adjusted p = 0.011)." (PMID 34122509, 2021). "Evaluation of the effects of SNP-SNP combinations on incident myopia revealed a statistically significant one-locus model: PTPN5 rs1550870 [cross-validation consistency (CVC) = 10/10, adjusted p = 0.0107]." (PMID 34122509, 2021). "Our findings suggest that PTPN5 rs1550870 and RASGRF1 rs6495367 are associated with the susceptibility to myopia and changes in several ocular parameters in southern Chinese children." (PMID 34122509, 2021). "In the present study, PTPN5 rs1550870 was found to be correlated with incident myopia, significant myopic shift and increasing LT as well as AL, but it had a negative effect on CCT." (PMID 34122509, 2021). "Evaluation of the effects of SNP-SNP combinations on incident myopia revealed a statistically significant one-locus model: PTPN5 rs1550870 [cross-validation consistency (CVC) = 10/10, p = 0.0107]." (PMID 34122509, 2021). "GMDR analyses demonstrated a significant correlation between the one-locus model (PTPN5 rs1550870) and incident myopia." (PMID 34122509, 2021). "By revealing the potential relationships between genes and miRNAs correlated with PDGFRA, RASGRF1, and PTPN5, this study may shed new light on myopia at the molecular level." (PMID 34122509, 2021). "Given that PTPN5 serves as a downstream component that adjusts the duration and functions of ERK signaling and that it is expressed specifically in rat RGCs, we hypothesize that the relationship of PTPN5 with myopia may be related to the role of DA in refractive error." (PMID 34122509, 2021).
triple-negative breast carcinoma (1 paper, 2018). An invasive breast carcinoma which is negative for expression of estrogen receptor (ER), progesterone receptor (PR), and human epidermal growth factor receptor 2 (HER2). "Taken together, these results indicate that restoration of PTPN5 function inhibits MAPK signaling in response to EGF treatment in tamoxifen sensitive, resistant and triple-negative breast cancer (TNBC) cells." (PMID 29590203, 2018).
uterine corpus endometrioid carcinoma (1 paper, 2013). "Protein tyrosine phosphatase non-receptor type 5 (Ptpn5) is highly expressed in muscle, uterus, skin and uterine corpus endometrioid carcinoma." (PMID 23468957, 2013).
tumor (10 papers, 2008 to 2024). "Taken together, these data indicate that restoring PTPN5 function inhibits BC cell growth in vitro and strongly suppresses tumor growth in vivo." (PMID 29590203, 2018). "Ptpn5, a novel upregulated gene in tamoxifen exposed MECs, was identified as a novel potential biomarker of tamoxifen response with tumor suppressor activity." (PMID 29590203, 2018). "Taken together, we hypothesized that PTPN5 and PTPN14 mainly function in the process of tumor progression, and its correlation with the risk of cancer requires further evaluation and experiments." (PMID 32536826, 2020). "Finally, we tested whether PTPN5 restoration suppressed tumor growth in vivo." (PMID 29590203, 2018). "We analyzed the expression levels of PTPNs in the TCGA database and discovered that PTPN1, PTPN6, PTPN7, PTPN18, PTPN20, and PTPN22 were significantly upregulated in tumor samples, while PTPN4, PTPN5, PTPN10, PTPN11, PTPN13, PTPN14, and PTPN21 were downregulated in tumor samples." (PMID 36226189, 2022). "For saliva samples, increased expression of protein tyrosine phosphatase non-receptor type 5 (PTPN5) was shown in all tumor groups compared with the CP group." (PMID 32928212, 2020). "The plausible explanation included the expression of PTPN5 in saliva was not originated from the tumor tissues while proteins in saliva can be produced from salivary glands or can also be transferred from systemic circulation." (PMID 32928212, 2020). "In our research, the results indicated that PTPN3, PTPN4, PTPN5 expression in normal tissues was lower than in PAAD tissues, but the tumor stage of PAAD patients did not affect the expression." (PMID 35154122, 2022).
cancer (4 papers, 2020 to 2023). A tumor composed of atypical neoplastic, often pleomorphic cells that invade other tissues. "Moreover, PTPNs expressions except for PTPN5, PTPN13, and PTPN21 were significantly upregulated in the tumorous compared with those in normal tissues in 20 cancers in the TCGA pan-cancer." (PMID 37884566, 2023).
neurological disorders (3 papers, 2021 to 2025). "Striatal-enriched protein tyrosine phosphatase (STEP, PTPN5) regulates synaptic function and neuronal plasticity in the brain and is a therapeutic target for several neurological disorders." (PMID 39605455, 2025).
neurodegenerative disease (2 papers, 2016 to 2023). A disorder of the central nervous system characterized by gradual and progressive loss of neural tissue and neurologic function. "PTPN3 is a potential immune checkpoint inhibitor target that may mediate T cells, while PTPN5 and PTPN7 can specifically inactivate MAPKs, so the developed inhibitors may have therapeutic potential for treating neurodegenerative diseases in AML patients." (PMID 37884566, 2023).
retinopathy (1 paper, 2020). "Nonetheless, at the same time, the Ptpn5 expression in the retina of both Wistar and OXYS rats at the age of 13 months was significantly higher than that at the age of 20 days (in the preclinical stage of AMD-like retinopathy)." (PMID 32707818, 2020).
PTPN5 also shares sentences with these, for which no sentence is quoted: fragile X syndrome (5 papers); autism (3); Cognitive impairment (3); Parkinson disease (3); leukaemia (2); psychiatric disorder (2); dementia (1); depression (1); Dravet syndrome (1); epileptic seizures (1); gastric cancer (1); intrahepatic cholangiocarcinoma (1); lung carcinoma (1); oral cancers (1); ovarian carcinoma (1); prostate carcinoma (1); stomach adenocarcinoma (1); Stroke (1); tauopathy (1); trauma (1); uveal melanoma (1).